NPC2 (NPC intracellular cholesterol transporter 2)
Diseases named in the same sentence as NPC2 in open-access papers (continued):
Sharing a sentence is not in itself a finding about the gene and the disease.
liver fibrosis (6 papers, 2016 to 2023). "Together these results suggest that HSCs, rather than hepatocytes, should serve as a major cause of alterations in liver fibrosis resulting from NPC2 down-regulation-induced free cholesterol accumulation." (PMID 27420058, 2016). "To determine whether NPC2 expression is associated with liver fibrosis, we used the mouse model in which liver fibrosis is produced by the i.p. injection of TAA." (PMID 27420058, 2016). "Our results support a novel role of NPC2 in HSCs activation, in that NPC2-dependent regulation is crucial for modulating the metabolism of free cholesterol and for activating HSCs during liver fibrosis." (PMID 27420058, 2016). "Since a high-cholesterol diet exacerbates liver fibrosis progression in both rodents and humans, we propose that the expression of NPC2 affects free cholesterol metabolism and regulates HSCs activation." (PMID 27420058, 2016). "In this study, we found that NPC2 is decreased in both thioacetamide- and carbon tetrachloride-induced liver fibrosis tissues." (PMID 27420058, 2016). "Moreover, a deficiency of the cholesterol metabolism-related gene Acyl-coenzyme A: cholesterol acyltransferase (ACAT1) or Niemann-Pick type C2 (NPC2) increases the levels of FC in HSCs, thereby exacerbating the progression of liver fibrosis." (PMID 37298640, 2023). "Since Nogo-B receptor (NgBR) can interact with and stabilize the NPC2, further studies are needed to elucidate whether NgBR regulates NPC2 level n in the pathogenesis of liver fibrosis." (PMID 27420058, 2016). "Accordingly, we hypothesized that the expression of NPC2 mediates free cholesterol accumulation and regulates HSCs activation and liver fibrosis." (PMID 27420058, 2016). "The authors concluded that NPC2 might prove an effective agent against liver fibrosis progression." (PMID 29522534, 2018). "Regulating NPC2 in HSCs may therefore represent a new treatment strategy for liver fibrosis." (PMID 29874879, 2018). "Regulation of NPC2 in HSCs may therefore represent a new treatment strategy for liver fibrosis." (PMID 29874879, 2018). "Regulating of NPC2 in HSCs may therefore represent a new treatment strategy for liver fibrosis." (PMID 27420058, 2016). "NPC2 overexpression may thus represent a new treatment strategy for liver fibrosis." (PMID 27420058, 2016). "In 2016, we reported that NPC2 is decreased in both thioacetimidic acid (TAA)- and CCl4-induced mouse liver fibrosis tissues." (PMID 29874879, 2018). "In the present study we found that NPC2 was down-regulated in both TAA- and CCl4-induced liver fibrosis tissues." (PMID 27420058, 2016). "The Q-PCR analyses showed that the mRNA levels of the liver fibrosis marker genes (α-SMA and Col1a2) were up-regulated in both male and female WT mice, while hepatic NPC2 was decreased." (PMID 27420058, 2016). "In this study we show that NPC2 is down-regulated in CCl4- and thioacetamide (TAA)-induced liver fibrosis tissues." (PMID 27420058, 2016). "NPC2 regulates intracellular cholesterol trafficking and homeostasis by directly binding with FC and expression of NPC2 is down-regulated in CCl4- and thioacetamide (TAA)-induced liver fibrosis tissues." (PMID 30483502, 2018). "However, both NPC1 and NPC2 were significantly up-regulated in biopsies from patients with liver fibrosis (F1-2) compared with patients without fibrosis." (PMID 29522534, 2018). "Since autophagy-lysosomal mediated breakdown of intracellular lipid droplets provides a key source of energy for fueling HSC activation, NPC2-mediated free cholesterol homeostasis may play a critical role in regulating HSC energy metabolism during HSC activation and liver fibrosis." (PMID 29874879, 2018). "However, the pathophysiological role of NPC2 in HSCs activation and liver fibrosis has not been defined previously." (PMID 27420058, 2016). "However, the molecular mechanisms of NPC2 in HSCs activation and liver fibrosis have not been explored in detail." (PMID 27420058, 2016).
liver fibrosis (continued). "Since the accumulation of free cholesterol in HSCs plays an important role in the progression of liver fibrosis and sensitizing HSCs to TGF-β1-induced activation, we tested whether overexpression of NPC2 decreases TGF-β1-induced HSCs activation under the condition of free cholesterol accumulation." (PMID 27420058, 2016). "However, the roles of NPC2 in liver fibrosis have not been explored in detail." (PMID 29874879, 2018). "However, the roles of NPC2 in HSCs activation and liver fibrosis have not been explored in detail." (PMID 27420058, 2016). "In this study, we found that NPC2 is decreased in CCl4- or TAA-induced liver fibrosis tissue, as well as in TGF-β1-treated HSCs, however the regulation mechanism of NPC2 is not clear." (PMID 27420058, 2016).
breast carcinoma (5 papers, 2013 to 2025). "Regarding to breast cancer, NPC2 up-regulation is associated with estrogen receptor (-), progesterone receptor (-) and human epidermal growth factor receptor (+)." (PMID 24147030, 2013). "These novel monoclonal antibodies should help with elucidating the roles of NPC2 in tumor development, especially in liver and breast cancers." (PMID 24147030, 2013). "Regarding to breast cancer, we further collected 33 invasive breast cancer subjects identified in the Kaohsiung Municipal Ta-Tung Hospital and analyzed the relationship between NPC2 expression and clinicopathological characteristics." (PMID 24147030, 2013). "Our study found that NPC2 over-expression is associated with HER-2 subtype, which suggests that NPC2 up-regulation may be a favorable prognosis predictor for breast cancer." (PMID 24147030, 2013). "NPC2 expression and clinicopathological characteristics of breast cancer patients." (PMID 24147030, 2013). "Validated down-regulated genes include NPC2 involved in the negative regulation of MAPK, TSPAN8 involved in tumor progression and metastasis, ANKRD1 mainly expressed in MDA-MB231 breast cancer cell lines and linked to treatment-resistance in breast cancer, and FST involved in metastasis suppression." (PMID 34680207, 2021).
frontotemporal dementia (5 papers, 2013 to 2020). Frontotemporal dementia (FTD) comprises a group of neurodegenerative disorders, characterized by progressive changes in behavior, executive dysfunction and language impairment, as a result of degeneration of the medial prefrontal and frontoinsular cortices. "Npc2, one of the genes causing frontotemporal dementia when mutated, is also part of this module." (PMID 29906661, 2018). "LAMP-1 shuttles between lysosomes, endosomes, and the plasma membrane and binds to cholesterol in association with Niemann-Pick disease type C1 (NPC1) and NPC2 proteins that export cholesterol from lysosomes." (PMID 32999035, 2020). "The gene Niemann-Pick disease, type C2 (NPC2) is upregulated in early disease and is connected to cathepsins L and B (CTSL, CTSB) and GLB1 in the lung network." (PMID 28330499, 2017).
Cirrhosis (4 papers, 2013 to 2021). A chronic disorder of the liver in which liver tissue becomes scarred and is partially replaced by regenerative nodules and fibrotic tissue resulting in loss of liver function. "Our previous study also showed that changes in the glycosylated pattern of NPC2 in serum were associated with cirrhosis and liver cancer." (PMID 34445279, 2021). "According to western blot data, the change of glycosylated pattern of NPC2 in serum is associated with cirrhosis and liver cancer." (PMID 24147030, 2013). "Further study is needed to clarify the roles of glycosylated NPC2 using more cirrhosis and HCC cases." (PMID 24147030, 2013). "By antigen-capture enzyme immunoassay ELISA, the serum NPC2 is increased in patients with cirrhosis and liver cancer." (PMID 24147030, 2013). "Since liver is the main source of plasma and biliary NPC2, the increase of sera NPC2 in cirrhosis and HCC patients may related to the severe damage of hepatocytes." (PMID 24147030, 2013). "In the present study we also observed changes in glycosylated NPC2 expression patterns in the sera of both cirrhosis and HCC patients, suggesting that such changes may serve as an indicator of liver cirrhosis and cancer." (PMID 24147030, 2013). "Since lipid accumulation and subsequently inflammation accelerate the progression of cirrhosis and liver cancer, NPC2 administration may ameliorate the liver cancer development." (PMID 24147030, 2013). "Importantly, patients with cirrhosis and HCC had significantly higher levels of NPC2 than healthy controls." (PMID 24147030, 2013). "We measured the amount of serum NPC2 level from 42 healthy controls, 20 patients with HBV chronic infection, 2 patients with HCV chronic infection, 27 patients with fatty liver, 28 patients with cirrhosis and 46 HCC using an ELISA." (PMID 24147030, 2013).
gastric cancer (4 papers, 2023 to 2025). A primary or metastatic malignant neoplasm involving the stomach. "The ROC curve analysis showed that NPC2 expression had a high diagnostic value for gastric cancer with AUC of 0.696." (PMID 38001127, 2023). "Our findings indicated that NPC2 expression is significantly associated with certain clinicopathological features and can serve as a promising prognostic biomarker for gastric cancer patients." (PMID 38001127, 2023). "Additionally, it is essential to evaluate the feasibility and accuracy of NPC2 expression as a diagnostic and therapeutic target in gastric cancer." (PMID 38001127, 2023). "The findings could provide new insights into the clinical significance of NPC2 expression in gastric cancer and its potential as a diagnostic and prognostic biomarker." (PMID 38001127, 2023). "Immunohistochemistry and qPCR results showed that NPC2 exhibited significant protein and mRNA expression in gastric cancer tissues." (PMID 40302802, 2025). "We used siRNA technology to suppress NPC2, resulting in reduced viability, proliferation, and invasion capacity of gastric cancer cells, as determined by CCK-8, colony formation, wound healing, and Transwell assays." (PMID 40302802, 2025). "Overall, these findings indicate that NPC2 enhances the movement and penetration of gastric cancer cells." (PMID 40302802, 2025). "It was found that NPC2 is a significant factor in gastric cancer and serves as a key prognostic factor." (PMID 40302802, 2025). "Western blot analysis was performed to assess the efficacy of the plasmid by transiently transfecting siNPC2 plasmid to investigate the role of NPC2 in gastric cancer." (PMID 40302802, 2025). "Further studies with larger sample sizes and longer follow-up periods are needed to validate our results and to determine the optimal cutoff value for NPC2 expression in gastric cancer patients." (PMID 38001127, 2023). "In the present study, we assessed the correlation between NPC2 expression and clinicopathologic characteristics in gastric cancer patients using data from The Cancer Genome Atlas (TCGA) database." (PMID 38001127, 2023). "Compared with normal gastric tissue, the NPC2 expression was significantly higher (P < 0.001) in gastric cancer." (PMID 38001127, 2023). "In this study, we aimed to assess the correlation between NPC2 expression in gastric cancer and clinicopathologic characteristics through analyzing data from the TCGA database." (PMID 38001127, 2023). "The higher NPC2 expression was observed in gastric cancer, compared with adjacent normal tissue (P < 0.001), confirmed by the IHC staining." (PMID 38001127, 2023). "The higher NPC2 expression was observed in gastric cancer, compared with adjacent normal tissue (P < 0.001)." (PMID 38001127, 2023). "The characteristics of patients with gastric cancer were evaluated in both groups according to high and low NPC2 expression." (PMID 38001127, 2023). "Our investigation has introduced an innovative risk prognostication model for cholesterol metabolism and verified the biological conduct of NPC2, a pivotal gene in cholesterol metabolism, thereby offering fresh modalities and viewpoints for gastric cancer treatment." (PMID 40302802, 2025). "Therefore, to clarify NPC2's role in gastric cancer and evaluate its potential as a therapeutic target, bioinformatics analysis and experimental validation were carried out around NPC2 in this work." (PMID 40302802, 2025). "Additionally, the study demonstrated that NPC2 promotes the progression of gastric cancer and the development of EMT." (PMID 40302802, 2025). "According to our findings, NPC2 expression was significantly upregulated in gastric cancer tissues and cell lines, and downregulation of NPC2 expression significantly reduced the ability of gastric cancer cells to proliferate, invade, migrate, and undergo epithelial-mesenchymal transition (EMT)." (PMID 40302802, 2025).
gastric cancer (continued). "We theorized that NPC2 could impact the course of epithelial-mesenchymal transition (EMT) in gastric cancer cells due to the importance of cholesterol metabolism-related genes in tumor migration and invasion in oncology research." (PMID 40302802, 2025). "Finally, the NPC2 expression was validated in the samples collected from patients and gastric cancer cell." (PMID 38001127, 2023). "The NPC2 expression was higher in gastric cancer than normal cells (P < 0.05)." (PMID 38001127, 2023). "The NPC2 expression was significantly higher (P < 0.001) in gastric cancer." (PMID 38001127, 2023). "The IHC staining further confirmed the high NPC2 expression in gastric cancer." (PMID 38001127, 2023). "In conclusion, our findings provide evidence that NPC2 expression may serve as a promising prognostic biomarker for patients with gastric cancer." (PMID 38001127, 2023). "The results suggest that NPC2 may serve as a novel biomarker for gastric cancer patients." (PMID 40302802, 2025). "However, the clinical significance and prognostic value of NPC2 expression in gastric cancer remain largely unknown." (PMID 38001127, 2023). "NPC2 expression may serve as a promising prognostic biomarker for patients with gastric cancer." (PMID 38001127, 2023). "BIRC5, CLDN1, DDX58, IL18, NPC2, NUSAP1, and PHC3 were found to have higher expression in gastric cancer tissues compared to normal tissues, and their expression was also elevated in various other cancer types." (PMID 40393971, 2025). "Consistent with our transcriptomic findings, LGALS9 treatment upregulated the expression of genes involved in cholesterol metabolism (NPC2, APOA) and PPAR signalling (SCD, PLIN2, FABP1), suggesting that LGALS9‐P4HB interaction modulates lipid metabolism in gastric cancer cells." (PMID 40534096, 2025). "Thus, we suggest that therapeutic targeting of NPC2 may enhance the prognosis for patients with gastric cancer and promote additional research to identify the precise mechanisms by which NPC2 regulates the development of GC." (PMID 40302802, 2025).
glioblastoma (4 papers, 2021 to 2024). The most malignant astrocytic tumor (WHO grade IV). "According to earlier research, abnormal NPC2 expression is significantly linked to a less favorable prognosis for glioblastoma." (PMID 39690926, 2024). "By stimulating the differentiation of tumor-associated macrophages (TAM) and modifying TME, NPC2 may improve the prognosis of human glioblastoma (GBM)." (PMID 38509982, 2024).
liver cancer (4 papers, 2013 to 2021). An epithelial or non-epithelial malignant neoplasm that arises from the liver. "Immunohistochemistry results of NPC2 expression in human breast, colon, lung, kidney and liver cancer paired tissues." (PMID 24147030, 2013). "In contrast, NPC2 was significantly down-regulated in renal cell carcinoma and liver cancer." (PMID 24147030, 2013). "In liver cancer tissues, NPC2 expression was downregulated in HCC patients, and lower NPC2 expression was correlated with higher vascular invasion and later stages of pathological grades." (PMID 34445279, 2021). "We have previously provided evidence that down-regulation of NPC2 is correlated with clinicopathological features and regulates ERK1/2 activation in liver cancer." (PMID 27420058, 2016).
liver cirrhosis (4 papers, 2013 to 2021). "For instance, macrophage activation is a common inflammatory cellular response in pneumonia, sepsis as well as liver cirrhosis, and occurs in concomitant with an increase in NPC2 secretion." (PMID 33723331, 2021). "Plasma NPC2 concentration was reported to be in the range of 2–5 ng/ml in healthy human subjects, and increase to as high as 15 ng/ml under pathological conditions, such as liver cirrhosis, hepatocellular carcinoma or atherosclerotic aneurysm." (PMID 33723331, 2021). "Previously, we reported that NPC2 was downregulated in liver cirrhosis tissues." (PMID 29874879, 2018).
Obesity (4 papers, 2010 to 2021). Accumulation of substantial excess body fat. "These novel roles of NPC2 open a new perspective in the study of the adipocyte dysfunction associated with obesity that needs to be studied in more detail." (PMID 21182758, 2010).
Pleural effusion (4 papers, 2011 to 2023). The presence of an excessive amount of fluid in the pleural cavity. "Another sample source for potential biomarker candidates is pleural effusion, where Niemann-Pick disease type C2 protein (NPC2), periostin, multimerin 2, CD166, and lysosome-associated membrane glycoprotein-2 (LAMP-2) were differentially expressed." (PMID 24550697, 2014). "Another potential diagnostic marker found in pleural effusions is NPC2 (Niemann-Pick disease type C2 protein), a protein that seems to be involved in regulating the transport of cholesterol." (PMID 22229091, 2011). "Proteomics analysis has also demonstrated that expression of NPC2 is increased in lung adenoma and pleural effusion." (PMID 24147030, 2013).
Alzheimer disease (3 papers, 2011 to 2022). A progressive, neurodegenerative disease characterized by loss of function and death of nerve cells in several areas of the brain leading to loss of cognitive function such as memory and language. "Niemann–Pick C disease is an autosomal recessive disorder caused by mutations in the NPC1 or NPC2 genes, which present clinical and neuropathological signs of Alzheimer's disease dementia." (PMID 35296367, 2022). "Therefore, it is interesting to examine whether addition of exogenous NPC2 protein restores disrupted papillary structures, such as epithelial atrophy of choroid plexus in Alzheimer disease." (PMID 21253586, 2011).
Fabry disease (3 papers, 2017 to 2021). Fabry disease (FD) is a progressive, inherited, multisystemic lysosomal storage disease characterized by specific neurological, cutaneous, renal, cardiovascular, cochleo-vestibular and cerebrovascular manifestations. "Reduced basal mTOR activity has also been observed in diverse models of lysosomal diseases including Neuronal Ceroid Lipofuscinosis type 3 lymphoblastoid cells, in NPC1- and NPC2-knockdown endothelial cells, in a Drosophila model of mucolipidosis IV, and a human podocyte model of Fabry disease." (PMID 34831346, 2021). "The first link between LSDs and Parkinson’s disease (PD) have been demonstrated a decade ago for Gaucher disease, and then extended to others, such as Niemann–Pick type I e II (NPC1, NPC2), GM1 and GM2 gangliosidosis, neuronal ceroid lipofuscinoses and Fabry disease." (PMID 28513549, 2017).